MMP9 (matrix metallopeptidase 9)
Diseases named in the same sentence as MMP9 in open-access papers (continued):
Sharing a sentence is not in itself a finding about the gene and the disease.
pancreatic cancer (continued). "In this study, based on the present findings, we inferred that HCS could inhibit the progression of advanced pancreatic cancer with liver metastasis through down-regulating the expression of VEGF, MMP-2 and MMP-9." (PMID 25496480, 2014). "MMP-2 rather than MMP-9 was activated in the metastatic pancreatic cancer, and it is secreted as an inactive zymogen and requires distinct activation processes." (PMID 25170871, 2014). "Subsequent inhibition of MMP-9 and IDO could partially restore NK cell function, suggested that these mediators promoted pancreatic tumor growth by suppressing NK cells." (PMID 25274283, 2014). "The PPARβ/δ-specific activator GW501516 and shRNAs to decrease expression of PPARβ/δ, BCL-6, and MMP-9 were used in two human pancreatic cancer cell lines, Miapaca-2 (COX-2 negative) and BxPc-3 (COX-2 positive)." (PMID 23737761, 2013). "MMP-9 from the family is constantly upregulated in a variety of human cancers, and this has aroused our interest to investigate the correlation of COX-2 with MMP-9 in pancreatic cancer." (PMID 21760774, 2011). "In addition, TQ could significantly inhibit the metastasis of pancreatic cancer in tumor-bearing mice and downregulate the positive expression of CD34, NF-κB, and MMP-9 in pancreatic tumors." (PMID 36686732, 2022). "To examine if there is a correlation between CCL21 and MMP-9, we performed Western blot analysis and demonstrated that CCL21 promoted MMP-9 protein expression in PANC-1 cells, suggesting that CCL21 plays a potential role in vasculogenesis and vascularization in pancreatic cancer." (PMID 29687228, 2020). "For example, MMP9 participated in pancreatic cancer angiogenesis and invasion; CXCL8 promoted invasiveness and angiogenesis in pancreatic cancer; ITGB1 was upregulated in pancreatic cancer and increased ITGB1 indicated a poor outcome; and STAT1 enhanced pancreatic cancer growth and metastasis." (PMID 31061236, 2019). "For example, M2-like TAMs can increase MMP2 and MMP9 activity in pancreatic cancer cells and decrease E-cadherin, indicating that EMT and Toll-like receptor (TLR) 4 expression and IL-10 production, are upregulated in M2-like TAMs to stimulate EMT when cocultured with pancreatic cancer cells." (PMID 30060755, 2018). "We speculated that TNC might regulate MMP9 expression and thus be involved in metastatic processes in pancreatic cancer, but we found that the expression of TNC did not affect MMP2 expression in these cells." (PMID 29088796, 2017). "We also detected that the protein levels of MMP2 and MMP9 were downregulated by miR-675-5p mimics in Patu8988 cells whereas miR-675-5p inhibitors upregulated MMP2 and MMP9 in SW1990 cells, suggesting that miR-675-5p can suppress the migration and invasion of pancreatic cancer." (PMID 28212565, 2017). "Previous studies have shown that NUAK1 activates MT1-MMP, which results in promoting the metastasis of breast and pancreatic cancer via activation of MMP-2 and MMP-9, so miR-203-driven invasion of HNSCC cells may be regulated by a pathway that is distinct from EMT induction." (PMID 26882562, 2016). "Although TN-C and MMP-9 have been thought to be related to invasion and metastasis of pancreatic cancer, it is unclear whether there is a co-expression of MMP-9 and TN-C in pancreatic cancer." (PMID 26652622, 2015). "Also, LIN28A overexpression resulted in upregulation of MMP2 and MMP9, while LIN28A knockdown downregulated the expression of MMP2 and MMP9 in PANC1 cells, indicating that LIN28A might be critical for invasion of pancreatic cancer cells." (PMID 26910839, 2016). "In pancreatic cancer, the overexpression of WT, but not DN, RNF13 in MiaPaca-2 cells led to increased matrix metallopeptidase 9 (MMP-9) activity, suggesting that the Ub ligase activity of RNF13 promotes metalloprotease function and cell invasion." (PMID 35159190, 2022).
pancreatic cancer (continued). "In the present study, we compared the expression levels of MMP-2, MMP-7, MMP-9 and MMP-13 in pancreatic cancer cells with and without leptin treatment." (PMID 25948792, 2015). "The expressions of MMP-9, DJ-1 and A1BG were confirmed by immunohistochemistry in 51 pancreatic cancer and 8 normal pancreas samples that were not included in the proteomic experiment." (PMID 18706098, 2008). "Notably, western blot analysis indicated upregulation of MMP2 expression in GnRH-inhibited Panc1 cells, whereas the regulation of MMP9 expression was not obvious, suggesting that MMP2 might play a role in GnRH-related invasion and migration in pancreatic cancer cells." (PMID 31263453, 2019).
bladder cancer (224 papers, 2006 to 2026). "Within the pathways associated with glyphosate-induced kidney injury, the bladder cancer pathway exhibits the lowest p-value, highlighting genes such as MMP9, MMP2, and SRC." (PMID 40851020, 2025). "TNF-α is also implicated in enhancing invasion and migration of bladder cancer cells by inducing matrix metalloproteinase-9 (MMP-9) release in the TME." (PMID 36140470, 2022). "There were 7 associations graded as moderate associations for cancer risk, including MMP-2 rs243865 with LC risk and PCa risk, MMP-7 rs11568818 with bladder cancer risk, and MMP-9 rs3918242 with BC risk and oral cancer risk." (PMID 35574300, 2022). "In a mouse bladder cancer model, ROS-induced metastasis by stimulating NF-κB has also been shown to be caused by ROS production and upregulation of NF-κB and MMP-9 in a mouse model." (PMID 34476214, 2021). "Previous studies showed that MMP-2 and MMP9 are associated with a high stage and grade of bladder cancer." (PMID 33923108, 2021). "Many studies support the notion that MMP-9 is closely linked to bladder cancer migratory and invasive capacity." (PMID 32708058, 2020). "MMP-9 activity is responsible for migratory and invasive potential and is deeply associated with bladder cancer progression." (PMID 32708058, 2020). "MMP-9 activity is closely linked with migratory and invasive potential and correlates with the occurrence and progression of bladder cancer." (PMID 31391858, 2019). "The ability of nimbolide to suppress the transcription factor-associated MMP-9 expression suggests that it has a role in preventing migration and invasion of bladder cancer cells." (PMID 31391858, 2019). "In two large epidemiologic studies, genetic changes in MMP9 gene were associated with the development of invasive bladder cancer and affected overall survival." (PMID 27317771, 2016). "The association between the urinary levels of MMP9 and risks of bladder cancer as well as stage and grade of disease was reported in different studies, but few studies are available for MMP3 levels in bladder cancer both schistosoma or non-schistosoma related." (PMID 25135219, 2014). "Evaluating the urinary levels of MMP3 and MMP9 as diagnostic and prognostic biomarkers in different stages of schistosomal and non schistosomal bladder cancer was the aim of the present study." (PMID 25135219, 2014). "The polymorphisms of MMP-1-1607 1G/2G, MMP-2-1306 C/T, and MMP-9-1562 C/T were reported to be related with bladder cancer susceptibility, but the conclusions remain to be inconsistent." (PMID 24390660, 2014). "TNF-α was shown to stimulate bladder cancer cells to produce MMP-9, which has been implicated in tumor invaαsion and metastasis." (PMID 23637926, 2013). "Recent advances in cancer cell biology have led to the association of MMP-2 and MMP-9 expression in bladder cancer progression." (PMID 22962576, 2012). "MMP2 is a statistically significant marker in blood plasma for bladder cancer detection with an increased diagnostic value in combination with MMP9 and TIMP1." (PMID 16901349, 2006). "It has been described in the literature that elevated expressions of MMP2 and MMP9 in bladder cancer tissue at the mRNA and protein level are associated with advanced tumour stage, grade, and a decreased survival rate." (PMID 16901349, 2006). "Therefore, MMP-9 has been the subject of several studies regarding the role of MMPs in bladder cancer as a screening/diagnostic and prognostic biomarker, making it an attractive therapeutic target in BCa." (PMID 41273852, 2025). "Another group further confirmed the association of MK2 with MMP2 by transfecting cancer cells with constitutively active MK2, demonstrating that this was associated with high MMP2 activity, and one more study also suggested that MK2 is associated with MMP2 and MMP9 activity in bladder cancer." (PMID 36558958, 2022).
bladder cancer (continued). "In addition, the high expression of ANGPT1, bFGF, MMP-9, and Tie-2 has been reported as an important prognostic factor for the high-risk group of bladder cancer patients." (PMID 36428758, 2022). "MMP9 is associated with high-grade and distant metastasis of bladder cancer." (PMID 34868901, 2021). "Moreover, induction of IL-8 secretion was associated with higher levels of MMP-2 and MMP-9 activity in endothelial cell and bladder cancer models." (PMID 34066355, 2021). "The present study reports the exact molecular mechanism of nimbolide-induced inhibition of proliferation, migration, and invasion mediated by altered cell cycle regulation, specific signaling pathways, and transcription factor-associated MMP-9 expression in bladder cancer cells." (PMID 31391858, 2019). "Furthermore, nimbolide-induced inhibition of migration and invasion in bladder cancer cells was caused by reduced MMP-9 expression, which was mediated by suppression of associated transcription factors." (PMID 31391858, 2019). "Besides, there are seven included studies reported the association between MMP2 and bladder cancer, and six investigations focused on MMP9." (PMID 28427222, 2017). "In this study, we investigated the mechanism of DATS-mediated inhibition of proliferation, migration, and invasion of EJ bladder cancer cells through comprehensive analysis of signaling pathways, cell cycle regulation, and transcription factor-associated MMP-9 regulation." (PMID 28680385, 2017). "The role of GOLPH3 in bladder cancer cell migration and invasion may associated with MMP9 expression, and its underlying mechanism needs to be explored further." (PMID 26375441, 2015). "In the current study, a total of five case–control studies with 1,141 cases and 1,069 controls were included in the meta-analysis, and the association between MMP-1-1607 1G/2G, MMP-2-1306 C/T, and MMP-9-1562 C/T polymorphisms and bladder cancer risk was explored." (PMID 24390660, 2014). "MMP3 may be the recommended urinary metalloproteinases as early diagnostic biomarker in the early stages of both types of bladder cancer although both MMP9 and MMP3 can be used in the diagnosis of advanced stages." (PMID 25135219, 2014). "But for the first time we could evaluate that MMP2 as a statistically significant marker in blood plasma for bladder cancer detection with an increased diagnostic value in combination with MMP9 and TIMP1." (PMID 16901349, 2006). "Therefore, the identification of specific miRNAs associated with EMT pathway and NGAL/MMP-9 complex may be useful to detect the development of bladder cancer at early stages." (PMID 27602581, 2016). "In bladder cancer, loss of GATA3 can induce EMT and the expression of pro-metastatic molecules, such as MMP-2 and MMP-9, leading to disease progression." (PMID 39781348, 2025). "This study aims to evaluate the combination effects of cisplatin, gemcitabine, and the APC/C inhibitor proTAME on cell migration as well as MMP2 and MMP9 expression in bladder cancer (RT4 cells) and normal epithelial cells (ARPE-19) as the control." (PMID 40136519, 2025). "Comparing MMP2 and MMP9, as potential bladder cancer biomarkers, both are suitable for T2 or higher stages of the disease, while both have failed at early stages." (PMID 41228251, 2025). "This process promotes the secretion of VEGFA and MMP9 by neutrophils, regulating lymphangiogenesis and thereby facilitating the lymphatic metastasis of bladder cancer." (PMID 40083688, 2025). "This indicated that CD46 facilitates bladder cancer cell migration and invasion via MMP9 expression." (PMID 40309774, 2025). "The present study examined the effects of reducing MMP-9 expression in T24-Luc bladder cancer cells using the CRISPR-Cas9 genome editing technique in an in vitro experimental setting." (PMID 41273852, 2025).
bladder cancer (continued). "This study evaluated the effects of cisplatin, gemcitabine, and the APC/C inhibitor proTAME, both individually and in combination, on cell migration and MMP2/MMP9 expression in RT4 bladder cancer and ARPE-19 normal epithelial cells." (PMID 40136519, 2025). "This study aimed to evaluate the effects of MMP-9 silencing using CRISPR-Cas9 in T24-luc bladder carcinoma cells." (PMID 41273852, 2025). "CRISPR-Cas9-mediated silencing of MMP-9 inhibited cell proliferation, migration, invasion, and increased apoptosis in BCa cells, supporting that MMP-9 has an important effect on the progression of bladder cancer." (PMID 41273852, 2025). "There have been several reports that the expression of MMP 9 changes during the bladder cancer development and that MMP9 and its dimer are overexpressed in high-grade bladder cancer samples in comparison with samples taken from patients with a lower grade." (PMID 41228251, 2025). "By impairing the N-cadherin-MMP9 pathway, miR-145 diminishes the migration and invasion capabilities of bladder cancer cells." (PMID 40689207, 2025). "In a similar experimental setting, the embryonic stem cell markers Oct-3/4 were also shown to increase MMP-9 expression, leading to the enhanced invasive and metastatic potential of bladder cancer cells." (PMID 41273852, 2025). "Because collagens are among the main components of the urinary bladder, the ability of MMP9 (along with other MMPs) to degrade collagens is a significant factor in urinary bladder cancer." (PMID 41228251, 2025). "Interleukin-20 induces the up-regulation of p21(WAF1) protein expression, which in turn causes nuclear factor (NF-B) to activate by promoting the migration of bladder cancer cells via ERK-mediated MMP-9 protein production." (PMID 38172584, 2024). "Mechanistically, transcription factor ETV4 enhances bladder cancer cells-derived CXCL1/8 to recruit TANs, increasing VEGFA and MMP9 secretion from TANs to promote lymphangiogenesis and lymphatic metastasis of bladder cancer." (PMID 39726782, 2024). "Osthole also decreased the levels of MMP2 and MMP9 proteins, which are involved in the bladder cancer cells invasion and migration abilities." (PMID 37069622, 2023). "The CXCL5/CXCL2 axis also promotes bladder cancer cell migration by upregulating MMP2/MMP9, which is an Akt-dependent pathway." (PMID 37373052, 2023). "Previous studies have revealed that MMP-9 is involved into the whole process of pathogenesis in bladder cancer; however, the present study has only focused on the occurrence of NIMBC." (PMID 36765767, 2023). "Research on bladder cancer and stromal cells demonstrated the MMP-9 expression and increased activity." (PMID 36979935, 2023). "Studies have demonstrated that MMP9 is a key prognostic factor for various cancers such as retinoblastoma, bladder cancer, and ovarian epithelial cancer." (PMID 36756017, 2023). "A similar amount of MMP-9 was found in LG cancer and a more than two times higher amount was found in HG urinary bladder cancer in comparison with the MMP-2 content." (PMID 36979935, 2023). "What still remains disputable is the potential significance of determination of the concentration of MMP-2 and MMP-9 in urine as an important predictor of urinary bladder cancer progression." (PMID 36979935, 2023). "Subsequently, we found that LINC00478 diminished the MMP9 expression via KDM1A recruitment in bladder cancer." (PMID 35504875, 2022). "Initially, our findings evidenced that LINC00478 was poorly expressed, while MMP9 was highly expressed in bladder cancer." (PMID 35504875, 2022). "Like its reported role in bladder cancer, a study found that MMP-9 is upregulated by CCR7 in the PCI-37B head and neck squamous carcinoma cell line." (PMID 35203305, 2022). "One meta-analysis has also found MMP-9 expression of bladder cancer tissue presented significant race diversity." (PMID 36387161, 2022).